ALB (albumin)
Diseases named in the same sentence as ALB in open-access papers (continued):
Sharing a sentence is not in itself a finding about the gene and the disease.
tumor (continued). "Furthermore,studies have showed that SPARC is an albumin-bound protein that is rich in tumormatrix and may plays an important role in absorbing Abraxane into the tumor site." (PMID 25239521, 2014). "Albumin demonstrates several appealing characteristics, including biocompatibility, nontoxicity, in vivo metabolism into innocuous degradation products, non-immunogenicity, purification feasibility, water solubility, a long circulatory half-life, and a tendency to accumulate in tumours." (PMID 25188308, 2014). "Therefore, in terms of OS, preoperative liver functions such as serum albumin and Child-Pugh class are important as patient-related factor and degree of tumor malignancy as tumor-related factor, showing the results similar to those in hepatitis virus-related HCC patients." (PMID 24745029, 2014). "In addition, tumor cells often have an increased rate of albumin uptake." (PMID 24278348, 2013). "Furthermore, we examined the relationships between the levels of Lunx mRNA and PH, LDH, glucose, albumin in the pleural effusion, histopathological category, and the degree of tumor cell differentiation, which referred to the degree of tumor cell differentiation close to normal cells." (PMID 23759037, 2013). "Similarly, only CRCTU Walker 256 inoculated and not ATCC Walker 256 inoculated brains showed a significant increase in albumin immunoreactivity following direct injection of tumour cells into the striatum when compared to the respective culture medium control group (p<0.001)." (PMID 23374226, 2013). "The lower serum albumin concentration in advanced cancer patients may be due to the release of some cytokines such as interleukin 6 or TNF, to suppression of hepatocyte production of albumin, or to increased capillary permeability to albumin by the tumor or its surrounding tissues." (PMID 22559838, 2012). "In the present study, in a much larger cohort, a low albumin alone was associated with poor survival in some tumours (breast, haematological and pulmonary) but not others (bladder, gynaecological, prostate, gastroesophageal, renal, colorectal, head and neck and hepatopancreaticobiliary)." (PMID 21266974, 2011). "Furthermore, a follow-up measure of albumin, after the systemic inflammatory response of treatment has resolved, may be of a value to establish whether treatment of the primary tumour has resulted in recovery of albumin concentrations." (PMID 17375036, 2007). "A lower serum albumin concentration (⩽43 g l−1) was associated with deprivation (P<0.05), hormonal receptor negative tumours (P<0.01) and significantly poorer 3-year relapse-free (85 vs 93%, P=0.001), cancer-specific (87 vs 97%, P<0.0001) and overall survival (84 vs 94%, P=0.001) rates." (PMID 17375036, 2007). "Lower serum albumin concentrations (⩽43 g l−1) were associated with deprivation (P<0.05), hormonal receptor negative tumours (P<0.01) and significantly poorer 3-year relapse-free (85 vs 93%, P=0.001) cancer-specific (87 vs 97%, P<0.0001) and overall survival (84 vs 94%, P=0.001) rates." (PMID 17375036, 2007). "However, the reliability using them as tumour markers have been challenged, because both albumin and α-FP are abundantly expressed in normal liver cells, they are released to the peripheral blood by either surgical injury of the liver for the disease other than HCC or by hepatitis virus infection." (PMID 11857021, 2002). "Rubidium-86, 125I-human serum albumin and 51Cr-labelled red cells have been used to investigate the effects of the anaesthetics Nembutal (pentobarbitone sodium) and urethane on blood perfusion, blood volume and albumin leakage in 5 types of transplanted mouse tumour and in normal organs." (PMID 1233083, 1975). "Additional independent factors for OS included albumin, LDH, peritoneal metastasis, age, tumor sidedness, and BMI." (PMID 42122963, 2026).
tumor (continued). "LASSO regression screened out 10 key prognostic factors: aspartate aminotransferase, total bilirubin, albumin (ALB), white blood cell count, DD, alpha-fetoprotein, CD4+ T cell count, PVTT, tumor number (≥3) and lymph node invasion." (PMID 42109683, 2026). "The albumin-to-carcinoembryonic antigen (CEA) ratio (ACR), a measure of nutritional-inflammatory status and tumor load, has emerged as a promising prognostic indicator." (PMID 41898226, 2026). "Combined clinico-radiological models-incorporating albumin-bilirubin (ALBI) grade, BCLC stage, alpha-fetoprotein (AFP) level, tumor diameter, distribution, and peritumoral arterial-phase enhancement-consistently outperformed single-source models." (PMID 42294337, 2026). "Such active targeting strengthens the accumulation of the albumin nanoplatforms in tumor tissue over the passive EPR-enhanced effect, increasing the drug concentration in the tumor while reducing systemic toxicity." (PMID 41489768, 2026). "Nanoparticle albumin‐bound (nab)‐paclitaxel is active in PD‐1 inhibitor‐naïve RM‐HNSCC and alters immune cells to potentially prime tumor response and reverse resistance to PD‐1 inhibitors." (PMID 41521502, 2026). "Collectively, Exo-BSA@dBET6 can exert anti-tumor effects by inhibiting BRD4 protein expression, and modification of dBET6 with exosomes and albumin nanoparticles markedly enhanced its anti-tumor efficacy in vitro." (PMID 41525248, 2026). "Mechanistically, Abraxane® leverages albumin’s interaction with gp60 and SPARC receptors to facilitate receptor-mediated transcytosis, enhance tumor accumulation, and increase intracellular drug delivery." (PMID 41489768, 2026). "Our analysis showed that ALB+KRT7+ epithelium in advanced alcohol‐related cirrhosis had increased Wnt activities, and inhibition of Wnt signalling can prevent the tumour promotion effect of ALB+ KRT7+ epithelium in organoid and murine models." (PMID 39834100, 2025). "Decreased serum albumin and globulin levels in EAC-bearing mice suggest impaired hepatic protein synthesis resulting from tumor-induced liver injury." (PMID 41011277, 2025). "While in ALB+KRT7+ epithelium from AC samples, in addition to cell proliferation‐related pathways (e.g., MAPK signalling), tumour‐related pathways were significantly enriched, suggesting malignant transformation potential." (PMID 39834100, 2025). "Finally, human serum albumin acted as a central anchor for the formation of the nanostructure through hydrophobic interaction but was also involved in the favoured accumulation of the nanostructure in the tumour due to the overexpression of albumin-binding protein on the membrane of cancer cells." (PMID 40143107, 2025). "We assessed quality of life (QOL) scores, albumin levels, and numerical rating scale (NRS) scores for stomatitis and tumor pain before and after QS to evaluate changes in NRS." (PMID 40988098, 2025). "Albumin mediated nanocarrier endocytosis and the nanocarrier significantly attenuated CT26 tumor growth." (PMID 39891180, 2025). "We also identified independent prognostic factors in the upfront surgery group, including tumor size ≥ 35 mm, CA19-9 level ≥ 250 U/mL, DUPAN-2 level ≥ 750 U/mL, albumin level ≤ 3.5 g/dL, and neutrophil-to-lymphocyte ratio ≥ 3.5." (PMID 39847284, 2025). "TBP3743 tumor-bearing mice were treated with albumin-conjugated caged MMAE, [99mTc]Tc-FAPI-34, or their combination, and tumor growth was monitored." (PMID 39753366, 2025). "Mean k1 values extracted from liver mask excluding gross tumor volume (liver-GTV) were correlated with Child-Pugh and albumin-bilirubin scores." (PMID 41022256, 2025). "The BALAD and BALAD-2 models, specifically developed for prognostication, incorporate both tumor biomarkers (AFP, AFP-L3%, and DCP) and liver function indicators (albumin and bilirubin)." (PMID 41228250, 2025).
tumor (continued). "As a nanoparticle albumin-bound formulation, nab-paclitaxel targets secreted protein acidic and rich in cysteine (SPARC) within the tumor stroma, reducing desmoplasia and enhancing vascular permeability—thereby improving gemcitabine delivery." (PMID 41040509, 2025). "In the SR cohort, maximum tumor size, INR, and AFP, albumin, PIVKA-II, and sodium levels were key factors (eFigure 1 in Supplement 1)." (PMID 40960824, 2025). "The hazard ratios of CS subtypes were similar to the tumor stage, which is often used to evaluate the patient’s prognosis in the clinic and were significantly superior to those of AFP, albumin (ALB) and PT (P < 0.05)." (PMID 40771801, 2025). "In the testing cohort, significant differences were found in PCOS, maximum tumor diameter, AFP, ALB, and HE4 levels." (PMID 41264387, 2025). "In the multivariate analysis, factors such as smoking, tumor type, TNM stage, chemotherapy, surgery, albumin levels, NCR, TBIL, neutrophil and platelet counts, and the PG-SGA score were identified as independent prognostic factors for survival." (PMID 40133874, 2025). "One of its key advantages is its ability to accumulate in tumor tissues via the enhanced permeability and retention (EPR) effect, making albumin particularly suitable for targeted cancer therapies." (PMID 40699702, 2025). "By integrating high LDH and low albumin, LAR captures both tumor aggressiveness and host vulnerability, making it a comprehensive predictor of bone marrow metastasis." (PMID 41156248, 2025). "In our cohort, both scores demonstrated significant correlations with CRP, albumin, CEA, CA19-9, and lymphocyte levels, highlighting their ability to reflect systemic inflammation, nutritional status, and tumor burden." (PMID 41517561, 2025). "This work employed albumin nanoreactor strategy to develop albumin nanocages with MTX and CS with protein corona and suitable PS for effective tumor- and LN-targeted cancer therapy and lung metastasis inhibition." (PMID 40908968, 2025). "Our study shows NMI binds to albumin but highly prefers MAOA, providing a plausible mechanism for systemic drug delivery via serum albumin to the tumor target and subsequent MAOA inhibition." (PMID 39904854, 2025). "The novel SHK-loaded nanoplatform, functionalized with albumin (BSA) and glycoside modification (gBSA/SHK), was designed to enhance stability and targeted delivery to tumor sites." (PMID 41272362, 2025). "Therefore, higher albumin levels may improve patient survival by inhibiting tumor progression." (PMID 41409247, 2025). "A key example is nab-paclitaxel (nab-PTX, Abraxane®), a ~130 nm nanoparticle conjugating paclitaxel with albumin, enhancing PTX solubility and tumor targeting via receptor-mediated uptake." (PMID 40801679, 2025). "According to the results of multivariate Cox regression analysis, it was observed that age, mean follow-up, neutrophil, albumin, CRP, CEA levels, and tumor characteristics (T-stage, N-stage, lymphovascular invasion) were all associated with survival outcomes." (PMID 40797479, 2025). "These include liver enzymes (ALT, AST, ALP), measures of synthetic and metabolic function (ALB, TP, TBIL), and general tumor markers (CEA, CA125, CA19-9)." (PMID 41211432, 2025). "By combining LDH and albumin, the LAR simultaneously captures tumor biology and the host’s systemic inflammatory-nutritional response, making it a more robust, multifaceted biomarker." (PMID 41255598, 2025). "In the validation cohort, tumor location, histological type, CEA, CA19-9, albumin, and VATI also differed significantly between groups." (PMID 40599844, 2025). "Pyropheophorbide-a loaded albumin nanoparticles (Ppa-loaded BSA NPs) enhance PDT by increasing neutrophil recruitment to tumor sites, improving drug accumulation, and suppressing tumor growth." (PMID 40227814, 2025).
tumor (continued). "Timed coadministration of caged-drug payload (albumin-conjugated caged MMAE) and radiopharmaceutical enabled tumor colocalization of the 2 agents, enhanced drug release in tumors, and reduced drug release by 20–3,000 times in off-target tissues." (PMID 39753366, 2025). "Then, ALB may be degraded to increase amino acid pools, eventually leading to increased mitochondrial ATP production to enhance cellular migration capacity, presumably while intrahepatic micro-metastasis increases tumor nodule number or size and/or further metastasis." (PMID 40186033, 2025). "Nano co-delivery system: Albumin nanoparticles co-loaded gemcitabine and MEK inhibitors, increasing the tumor/plasma drug concentration ratio to 9.8:1, significantly inhibiting the activation of the MAPK pathway." (PMID 41293424, 2025). "The lactate dehydrogenase-to-albumin ratio (LAR), a composite marker that reflects both tumor metabolism and the host’s nutritional-inflammatory status, has demonstrated prognostic value in several cancers." (PMID 41255598, 2025). "By blending tumor-intrinsic signals (serum tumor marker, size, multiplicity) with host-response metrics (NLR, albumin, γ-GT), our model captures complementary invasion pathways that neither domain alone can fully describe." (PMID 41331584, 2025). "The most abundant blood protein, albumin, was readily detected in the ~ 65 kD NMI labeled band of NMI treated MC-38 tumor tissues with 54 unique peptide sequences identified from 658 peptide spectrum matches." (PMID 39904854, 2025). "There was a significant difference between the groups in CA15-3, CEA, albumin, ALP, neutrophil count, lymphocyte count, tumor diameter, NLR, SII, T stage, and N stage (p < 0.05)." (PMID 41398653, 2025). "ALB+KRT7+ epithelium from advanced ALD had malignant transformation potential and tumour promotion activity." (PMID 39834100, 2025). "In the univariate analysis, albumin (ALB) levels (P = 0.031), CA19-9 levels (P = 0.006), tumor size (P = 0.001), PS score (P = 0.008), and presence of satellite lesions (P = 0.010) were identified as factors associated with early HCC recurrence." (PMID 40595796, 2025). "When using [90Y]Y microspheres, dose prediction is calculated through a 99mTechnitium ([99mTc]Tc)-macroaggregated albumin (MAA) scan, which allows the calculation of the dose to be administered to the tumour." (PMID 41263849, 2025). "We examined ECOG PS, tumor site, histology, clinical tumor stage, opioid use, bleeding, initial QOL, albumin, and gross tumor volume." (PMID 40988098, 2025). "Specifically, ALB and CYP2E1 were highly expressed in normal areas, GPC3 and AKR1B10 were highly expressed in tumor areas, ACTA2 and COL1A1 were highly expressed in fibrostic areas, and PTPRC was highly expressed in inflammation areas." (PMID 40051627, 2025). "Thus, reduced ALB may contribute to tumor aggressiveness through inflammatory mechanisms." (PMID 41291156, 2025). "The system employs albumin nanoparticles loaded with gemcitabine, which exploit the SPARC protein and gp60 receptor mediated pathways for preferential tumor cell uptake." (PMID 41293424, 2025). "patient age, CEA levels, lymphocyte count, albumin, NLR, SII, PNI, tumor distance from the anal verge, tumor length, tumor involvement of the bowel circumference, cT stage, cN stage, TRG grade, KRAS status, and MSI status were correlated with survival." (PMID 40444087, 2025). "Based on the results of univariate and multivariate logistic regression analysis of the training cohort data, we constructed a nomogram for PNI, albumin levels, ASA, and tumor diameter." (PMID 39568563, 2024). "GP60 is expressed on vascular endothelial cells and enables albumin to cross the vascular endothelial cell layer, and SPARC is overexpressed in many types of tumor cells, while it is minimally expressed in normal tissue cells." (PMID 38323081, 2024).
tumor (continued). "In this study, we included 29 hematological factors and ultimately identified four factors to establish a hematological model, namely, LYM, ALB, HDL, and NLR, which have been reported in previous tumor immunotherapy studies." (PMID 38609892, 2024). "Tumor-induced cytokines such as TNF-α, interleukin 1 beta, and IL-6 contribute to the inhibition of albumin gene expression in cachexia." (PMID 38339365, 2024). "Considering the HAP-III model, we finally selected five factors, including log AFP, ALB, Log TBLT, major tumor size and intrahepatic lesion number, to develop a deepHAP IV model." (PMID 38434985, 2024). "For chromatin accessibility data of scCPA‐Tag, the cluster exhibiting high gene activity scores for ALB, TTR, and APOA2 was identified as tumour cell." (PMID 39210544, 2024). "Normal liver cells and tumor cells clusters were extracted for separate UMAP clustering and further classified by AFP, PTPRC, ALB, GPC3." (PMID 39015573, 2024). "The main reason for this effect was that albumin nanoparticles utilized the GP60- and SPARC-mediated pathway for targeted DOX delivery, and the effect resulted in significant inhibition of tumor growth and lower exposure of major organs to DOX." (PMID 38323081, 2024). "Potential confounding factors were adjusted using a multivariable Cox regression analysis, which included age, gender, tumor location, stage, ECOG PS, baseline albumin, baseline CA 19.9, year of diagnosis, and enrollment in the clinical trial." (PMID 38350919, 2024). "The HPCL group had a significant increase in ALP, ALT, AST, GGT, T. Bilirubin, D. Bilirubin, and Albumin, in addition to the lipid profile (TC, TG, HDL-C, and LDL-C) and the AFP, the tumor marker, in comparison to the control group (p < 0.05)." (PMID 39479501, 2024). "It cannot be excluded that GRPR-mediateduptake of [111In]In-ABD-RM26 Gen 2A in tumors constitutesonly part of the overall tumor uptake and the enhanced permeabilityand retention (EPR) effect of the albumin-ABD-RM26 adduct constitutesthe rest." (PMID 39220525, 2024). "Five variables were included in the model: the size of the tumor, BCLC B sub-classification, AFP, ALB, and the number of lesions." (PMID 38434985, 2024). "The experimental results showed that albumin nanoparticles modified by the technology of reverse QTY code can maintain its biological activities and target tumor tissue or cells efficiently via the GP60 receptor and SPARC pathway." (PMID 38323081, 2024). "There were no statistical differences in age, sex, BMI, preoperative hemoglobin (Hb), WBC, albumin (ALB), prealbumin (preALB), globulin (GLB), tumor location, tumor staging, types of surgery, resection, and reconstruction between the study and control groups." (PMID 39281267, 2024). "Five parameters, log AFP, ALB, Log TBLT, major tumor size, and intrahepatic lesion number, were assessed and identified as predictors and used in model construction." (PMID 38434985, 2024). "Following LASSO regression screening, ALP, preoperation AFP, ALB, PT, PNI, tumor size, and tumor number were identified as closely related to the OS of HCC patients after ablation." (PMID 39440446, 2024). "The current European Association of Urology (EAU) guidelines propose using the neutrophil–lymphocyte ratio (NLR), albumin, C-reactive protein (CRP), De Ritis ratio, renal function and fibrinogen as prognostic indicators of tumor progression." (PMID 39272712, 2024). "The baseline characteristics, including sex, age, tumor location, stage, family history, ECOG, albumin, CA-19.9 and 1L chemotherapy regimens, platinum-based or platinum-free chemotherapy were not significantly different between patients with or without gHRmut." (PMID 38350919, 2024). "Pre-operative tumor marker levels and inflammatory markers [C-reactive protein - CRP, albumin, absolute neutrophil count (ANC), absolute lymphocyte count (ALC), absolute platelet count (APC)] and patient history were retrieved using MedSolution database." (PMID 38645565, 2024).